STAT3 (signal transducer and activator of transcription 3)
Diseases named in the same sentence as STAT3 in open-access papers (continued):
Sharing a sentence is not in itself a finding about the gene and the disease.
tumor (continued). "Additionally, macrophage activity is modulated by tumour cell transcription factors, such as NF-κB and STAT3." (PMID 40407951, 2025). "Precision medicine approaches integrating STAT3 modulation with genetic and epigenetic tumor markers could optimize patient stratification and treatment efficacy." (PMID 40860906, 2025). "In animal studies, treatment with STAT3 inhibitors (such as WP1066) has been shown to significantly reduce the accumulation of MDSCs in murine tumor models, while restoring T cell proliferation and cytotoxic activity, supporting the potential of this pathway as a therapeutic target." (PMID 41333481, 2025). "STAT3’s central role in maintaining immune homeostasis, particularly in anti-tumor immunity, further complicates therapeutic targeting, as systemic inhibition may result in unintended immunosuppressive effects." (PMID 40704145, 2025). "STAT3 is often over-activated in tumor-infiltrating immune cells, negatively regulating neutrophils, natural killer cells, effector T-cells, and dendritic cells, while positively regulating regulatory T-cells and myeloid-derived suppressor cell (MDSC) populations, thereby affecting immune function." (PMID 40568576, 2025). "This was consistent with the previously reported mechanism that CHK1 regulates PD-L1 through STAT3, suggesting that CHK1 might regulate PD-L1 expression via the JAK-STAT/STAT3 pathway and participate in tumor immune evasion." (PMID 40573296, 2025). "In this study, we found for the first time that the NF-κB and STAT3 signaling pathways may play a role in upregulating PD-L1 expression on tumor VECs in NPC." (PMID 40000620, 2025). "We present evidence that STAT3 supports tumor growth following KRAS depletion." (PMID 40859018, 2025). "Additionally, feedback loops exist wherein STAT3 upregulates components that further amplify mTOR signaling, thereby promoting tumor progression." (PMID 40806360, 2025). "In addition, M2 macrophages decreased the anti-tumor effects of vinorelbine by upregulating p-STAT3 and p-EGFR and downregulating BAX." (PMID 40076874, 2025). "Its ability to suppress T-cell activation leads to the successful immune evasion of the tumor while its contribution to the prompting of pathways such as the PI3K/Akt and STAT3 pathways can enhance survival and proliferation, further increasing the tumor’s resistance." (PMID 40129921, 2025). "Additionally, the Let-7 family of miRNAs acts as tumor suppressors by inhibiting STAT3 expression, thereby hindering tumorigenesis and metastasis." (PMID 40438109, 2025). "The activation of the STAT1 and STAT3 signaling pathways in tumor cells, along with the mediation of iNOS expression by M-MDSCs, may contribute to the induction of the EMT/CSC phenotype." (PMID 41368628, 2025). "Western blot results suggested that the NF-κB pathway inhibitors could downregulate p-P65, p-STAT3, and PD-L1 on HUVECs treated with tumor supernatants." (PMID 40000620, 2025). "For instance, IL-6 produced by senescent tumor-associated fibroblasts facilitated EMT and chemoresistance in oral squamous cell carcinoma (OSCC), a major subtype of HNCs, through activation of the JAK/STAT3 pathway." (PMID 41463272, 2025). "Notably, the combination treatment significantly inhibits tumor growth by targeting the EGFR/JAK/STAT3 signaling pathway, contributing to the reduction of PD-L1 expression associated with immune evasion." (PMID 40347254, 2025). "EGFR activates mTORC1 via the PI3K/AKT pathway, upregulating glutaminase (GLS) to fuel nucleotide synthesis, while STAT3-mediated cell cycle progression creates a self-reinforcing loop that provides both biosynthetic precursors and proliferative signals for rapid tumor growth." (PMID 40904507, 2025).
tumor (continued). "In this process, the activation of nuclear factor kappa-light-chain-enhancer of activated B cells (NFκB) and signal transducer and activator of transcription 3 (STAT3) plays a critical role in mediating refractoriness to chemotherapeutics and promoting the mesenchymal attributes of tumor cells." (PMID 40149313, 2025). "Notably, previous studies reported that STAT3 promotes PD-L1 transcription, linking it to tumor immune evasion." (PMID 40975978, 2025). "Furthermore, accumulating evidence underscores constitutive STAT3 activation in orchestrating tumor-mediated immunosuppression through multifaceted mechanisms." (PMID 41280323, 2025). "Cytokines secreted from immune cells surrounding tumor cells can influence STAT3 activation." (PMID 41104968, 2025). "In addition, the HIF-1 signaling pathway shows the regulation of STAT3 after IL-6 stimulation, which shows the potential of BO in regulating immunity to achieve tumor treatment." (PMID 40076902, 2025). "STAT3 plays a well-known role in the process of tumor formation." (PMID 40458725, 2025). "circ-STAT3 promotes the proliferation, invasion, migration, stemness, and tumor growth of HB cells by upregulating STAT3 and Gli2, suggesting that circ-STAT3 may be a biomarker for HB." (PMID 41393242, 2025). "Furthermore, concurrent activation of STAT3 and STAT5 is associated with more favorable tumor types compared to tumors with activated STAT3 alone, suggesting that the relationship between these two STATs is critical." (PMID 40507264, 2025). "Specifically, proteomic analyses have revealed several CAAT-derived factors, such as leptin and insulin-like growth factor binding protein 2 (IGFBP2), which activate pro-oncogenic pathways, including the PI3K/AKT and STAT3, thereby promoting tumour growth and resistance to therapy." (PMID 41388212, 2025). "STAT3 is a key transcription factor in inflammatory and tumor signaling, and its dysregulation may contribute to tumor progression by impairing effective immune responses." (PMID 40733498, 2025). "Furthermore, both HYP and X-ray markedly reduced the phosphorylation levels of ERK, AKT, and STAT3 proteins in tumor tissues." (PMID 39558814, 2025). "Importantly, these effects were recapitulated in tumor tissues, where treatment reduced both STAT3 activation and expression of downstream signaling proteins." (PMID 40347254, 2025). "Importantly, the potential anti-tumor mechanisms of STA confirm that the JAK2/STAT3 pathway in macrophages is a potential therapeutic target." (PMID 39974738, 2025). "STAT3 is also a key mediator of oncogene addiction and supports the self-renewal of tumor-initiating cancer stem cells, contributing to cancer initiation, maintenance, and relapse in several tumor types." (PMID 39792482, 2025). "In addition to promoting PD-L1 expression, NF-κB and STAT3 contribute to immune escape and tumor progression by inhibiting apoptosis." (PMID 40999385, 2025). "In metastatic breast cancer, elevated MAFF expression was associated with activation of the IL-11/signal transducer and activator of transcription 3 (STAT3) pathway, and inhibition of MAFF expression reduced tumor metastasis, suggesting a role in promoting tumor invasion and dissemination." (PMID 41146237, 2025). "Furthermore, there are no reports in the literature on the combined effect of inhibitors of the redox domain of APE1 and STAT3 on the invasive potential of tumor cells." (PMID 41090323, 2025). "In addition to affecting immune cells, curcumin can directly target tumor cells by inhibiting STAT3-mediated proliferation and survival signals, thus slowing down tumor growth." (PMID 40989587, 2025).
tumor (continued). "Mechanistically, ALI may affect prognosis through two pathways: firstly, high NLR reflects systemic inflammation, which promotes the release of pro-inflammatory cytokines (such as IL-6, TNF-α) and drives tumor invasion via the STAT3 pathway." (PMID 40535131, 2025). "Additionally, HMGB1 encapsulated by gastric cancer-derived EVs activates STAT3 signaling in neutrophils to upregulate PD-L1 expression, which suppresses T cell proliferation, activation and anti-tumor functions." (PMID 40908470, 2025). "Based on these data, we inferred that Con-A + SB-treated cells had significantly lower expression levels of proteins linked to tumor formation, such as JAK1, STAT3, PCNA, cyclin D1, along with evidence of G2/M phase arrest, as indicated by the downregulation of Cyclin B and Cdk1." (PMID 40350446, 2025). "Notably, increasing evidence highlights aberrant activation of the IL-6/STAT3 signaling pathway as a key contributor to tumor growth and resistance to therapy in cancer." (PMID 41148817, 2025). "Most groups have shown that late stage blocking of STAT3 is favorable for tumor clearance." (PMID 40356899, 2025). "Further in vivo studies will better clarify CSC inhibition and assess whether combining mCHT with EZH2- or STAT3-targeted agents could improve long-term tumor control." (PMID 41516003, 2025). "HPRT1 also promotes EMT and tumor proliferation through STAT3 interaction." (PMID 40699765, 2025). "Importantly, preclinical studies have demonstrated that blockade of the IL-6/STAT3 axis restores anti-tumor immune responses by relieving T cell suppression and enhancing adaptive immunity." (PMID 40704145, 2025). "The JAK/STAT3 signaling pathway has been found discovered to be activated in a number of malignancies, particularly colorectal cancer playing an important part in maintaining the tumor microenvironment." (PMID 40161370, 2025). "Immunohistochemical results showed that CAF could promote elevated levels of KI67 and p-STAT3 in tumor, which was reversed by LL1 in combination with osimertinib." (PMID 40703348, 2025). "Furthermore, tumor formation in 4T1 cells supports that the cytoplasmic HMGB1 expression is related to p-STAT3 and PD-L1 expression." (PMID 40389855, 2025). "The inhibition of the Jak2/Stat3 signaling pathway represents a promising therapeutic approach for NB, as it not only blocks survival signals but also interferes with mechanisms that promote tumor invasion and metastasis." (PMID 40429864, 2025). "In immune cells, STAT3 signaling encourages autocrine production of IL-6 that sustains tumor-promoting inflammation along with immunosuppressive factors such as IL-10 and TGFβ which blunt the anti-tumor response." (PMID 40356899, 2025). "Importantly, we observed that neutrophil-specific STAT3 knockout significantly impaired tumor growth in both cancer models, suggesting its pancancer effect." (PMID 40885734, 2025). "Notably, as a key hub linking extracellular signaling with intranuclear transcriptional regulation, the activity status of STAT3 directly affects the proliferation, survival, and metabolic reprogramming of tumor cells." (PMID 40799250, 2025). "Subsequent transcriptomic analysis of CC tissues (n = 9) and their paired adjacent non-tumor tissues revealed a substantial upregulation of key genes involved in the Src/AKT/STAT3 pathway, along with elevated EFNA1 expression in tumor samples compared with normal tissues." (PMID 39964764, 2025). "Furthermore, exosomal miR-19b-3p from LUAD cells induces M2 macrophage polarization by targeting PTPRD proteins to activate STAT3 signaling, supporting lung metastasis of tumor cells." (PMID 40028322, 2025). "Immunofluorescence analysis revealed that M@CuB-Lips significantly suppressed the expression level of p-STAT3 in the tumor site, which may represent a crucial mechanism of CuB’s antitumor activity against GBM." (PMID 41145734, 2025).
tumor (continued). "Notably, D-PROTAC also elicits downregulation of various downstream target genes regulated by STAT3, resulting in cell cycle arrest, apoptosis promotion, inhibition of tumor migration and proliferation, and suppression of tumor immune evasion." (PMID 40118821, 2025). "Within tumors, IL-6 is known to stimulate tumor growth, survival, angiogenesis, and evasion of immune detection via IL-6/STAT3 signaling, as well as to enhance and propagate oncogenic signals within the TME, thereby promoting tumorigenesis, invasion, and metastasis." (PMID 39652104, 2025). "And constitutionally activated STAT3 signaling pathways in many cancers contribute to many markers of carcinogenesis and metastasis, including promoting tumor cell proliferation and enhancing the ability of cells to migrate and invade into extracellular matrix." (PMID 41425852, 2025). "Treatment with an STAT3-specific activator partially reversed the tumor-suppressive effects of APOC2 knockdown, supporting the hypothesis that JAK2/STAT3 is a key downstream effector of APOC2." (PMID 41296440, 2025). "In conclusion, our results suggest that hypoxia-induced suppression of UPF1 expression decreases NMD efficiency, leading to the stabilization of COX-2 and PD-L1 mRNAs, thus activating the p38/MAPK and JAK2/STAT3 pathways and promoting tumor progression in NPC cells." (PMID 41293174, 2025). "Indeed, STAT3 is a key protein that has the role of a transcriptional factor, influencing cell proliferation and solid tumor metastasization through tumor microenvironment involvement." (PMID 41441207, 2025). "In addition, verteporfin treatment resulted in the downregulation of tumor p-STAT3 and PD-L1 expression, along with YAP and CTGF, highlighting the ability of verteporfin to modulate PD-L1 expression in HR tumors." (PMID 40542295, 2025). "Additionally, results from the proteomic analysis of serum from tumor-bearing mice indicate that AGER inhibition affects metastatic mechanisms by decreasing the expression of STAT3 and AKT." (PMID 40647480, 2025). "However, in the TME, persistent activation of STAT3 leads to the polarization of macrophages toward the M2 phenotype, thereby promoting tumor growth and metastasis." (PMID 40989587, 2025). "Furthermore, it alters the tumor immune landscape by targeting MDSCs through modulation of the Arginase 1 (Arg-1)/inducible nitric oxide synthase/STAT3 axis and related signaling pathways." (PMID 40869364, 2025). "EFNA1 drives tumor progression through Src/AKT/STAT3 pathway activation." (PMID 39964764, 2025). "Notably, this increase in TGFβ secretion was counteracted by pharmacological inhibition of STAT3 using STAT3-IN-12, indicating that tumor-conditioned media induce TGFβ production in a STAT3-dependent manner." (PMID 41514627, 2025). "Beyond general cytokine signaling, candidate pathways may include the IL-6/STAT3 axis and TGF-β signaling, both of which are implicated in tumor–stroma–osteoclast crosstalk in related cancer models." (PMID 41153834, 2025). "Taken together, blocking IL-19 could disturb the canonical IL-19/STAT3 pathway and weaken immunosuppressive tumor microenvironment in GBM." (PMID 40057744, 2025). "In addition, ADRr tumor cells showed more formation of p-STAT3/MSN complex that translocated to the nucleus compared to the TNBC cell lines without ADR resistance and the complex was enhanced by IL-6 stimulation." (PMID 40696387, 2025). "Moreover, the Tregs helps in activation of the STAT3 pathway by acting on tumor cells to promote immune evasion and tumor growth." (PMID 40558596, 2025).
tumor (continued). "However, IL-17 promotes tumor growth by maintaining an inhibitory inflammatory environment through tumor angiogenesis, and by activating the STAT3 and NF-κB pathways to promote the expression of anti-apoptotic genes." (PMID 39980556, 2025). "Silibinin exerts multifaceted anticancer effects by suppressing PD-L1 expression through the inhibition of JAK/STAT3 signaling and MUC1-C interaction, attenuating NF-κB-driven inflammation, and downregulating CCL2-mediated recruitment of tumor-associated macrophages (TAMs)." (PMID 40650040, 2025). "Furthermore, Calanquinone A suppresses tumor formation in vivo, likely through direct interaction with STAT3." (PMID 40759869, 2025). "Hence, inhibition of STAT3 has been shown to reduce MDSC populations, thereby enhancing antitumor immunity; b) Polarization of tumor-associated macrophages (TAMs)." (PMID 40881676, 2025). "Extensive mechanism studies have shown that curcumin can regulate various intracellular signaling pathways essential for cancer cell survival, growth, and invasion, such as NF-κB, JAK2/STAT3, and PI3K/AKT signalings, which underlies its broad tumor-suppressing effects against multiple cancer types." (PMID 40447190, 2025). "Exosomal miR-423-3p derived from cervical cancer can also inhibit STAT3 phosphorylation by targeting cyclin-dependent kinase 4, which inhibits M2 polarization of macrophages and reduces IL-6 expression, which in turn inhibits tumor progression." (PMID 40612677, 2025). "Conversely, lincRNA‐p21 functions as a tumor suppressor by inhibiting JAK2/STAT3 signaling." (PMID 40231344, 2025). "On the one hand, targeting IL−6/JAK/STAT3 signaling might improve the efficacy of ICIs as a result of direct inhibitory effects on tumor cells as well as effects on immune cells in the tumor microenvironment." (PMID 40255422, 2025). "Additionally, CA prevented the polarization of macrophages into the M2 phenotype, a macrophage subtype that supports tumor progression through STAT3 activation in cancer cells." (PMID 40330466, 2025). "Nuclear FoxO1 acts as a transcriptional repressor to downregulate JAK1/JAK2 expression, leading to reduced STAT3 phosphorylation at Tyr705, as demonstrated by Western blot and immunohistochemistry, which effectively disrupts a key survival pathway in hypoxic tumor cells." (PMID 40806463, 2025). "First, GABA receptor inhibitors (such as bicuculline and biculin) may inhibit tumor progression by blocking GABRP‐mediated signal transduction (such as PI3K/AKT or STAT3 pathways)." (PMID 40459297, 2025). "Conversely, TXNIP could suppress tumor growth by upregulating IL-24 and downregulating p-STAT3 signaling." (PMID 40175348, 2025). "Following 48 h of exposure, the tumor cells were analyzed for the expression of apoptosis and proliferation markers, such as Caspase-9 and Ki-67, as well as markers associated with cisplatin resistance, including APEX1, MTDH, ERK1, and STAT3." (PMID 40149331, 2025). "Indeed, compared to the siControl RNA group, the level of STAT3 in tumor cells transfected with siSNRPE RNA was markedly decreased." (PMID 40386046, 2025). "Targeted knockout of DMT1 inhibits iron uptake by colon epithelial cells, disrupts the iron-regulated signaling pathway mediated by CDK1, JAK1 and STAT3, and consequently suppresses tumor cell proliferation in colon cancer mouse models, thereby reducing tumor burden." (PMID 40144390, 2025). "The IL-6/STAT3 pathway plays a role in promoting tumor growth and metastasis in various cancers, and thus its inhibition may slow the progression of HCC." (PMID 40919140, 2025). "Studies have shown that increased STAT3 expression contributes to tumor growth and metastasis." (PMID 40860906, 2025). "Interestingly, the interleukin (IL)-6/Janus kinase (JAK)/STAT3 pathway was reported to contribute to tumor formation and progression in HNSCC by inducing the EMT." (PMID 40113769, 2025). "SIRT2 promotes tumor angiogenesis by regulating STAT3/VEGFA pathway." (PMID 40746889, 2025).